CD99 (CD99 molecule (Xg blood group))
Diseases named in the same sentence as CD99 in open-access papers (continued):
Sharing a sentence is not in itself a finding about the gene and the disease.
tumor (continued). "Although they did not claim the tumor type of the transformed hMSC‐TERT20 was OS, these tumors contained osteoid and expressed α‐SMA and CD99 41, indicating the similarity to OS." (PMID 28191765, 2017). "Histological evaluation of the septated, cystic mass revealed tumour cells forming an irregular patternless pattern; immunohistochemically, the cells tested positive for vimentin, CD34, CD99 and STAT6 but negative for keratin (AE1-AE3), CD31 and S100." (PMID 28865431, 2017). "The tumor cells expressed CD34, bcl-2, CD99, and vimentin and were negative for LCA (leukocyte common antigen), desmin, SMA (smooth muscle antigen), CK7, CK34, BE12, CK19, and CK20." (PMID 25688313, 2015). "In the present case, immunohistochemistry revealed that the tumor was positive for GFAP, S-100 protein, vimentin, CD34, CD99 and D2-40 and negative for neuron markers (Syn and chromaffin protein/NeuN)." (PMID 24348765, 2014). "Immunohistochemically, the tumor cells were positive for S-100 protein, vimentin and BCL-2, and negative for HMB45, Melan-A, CD117, CD34 and CD99." (PMID 25364450, 2014). "Immunostaining showed that the tumor was positive for the Vimentin, Desmin and MyoD1, and was negative for CK, P63, NSE, CD45, CD30, S-100, CD99, Myoglobin, CD68, CD34, CD31, and α–SMA." (PMID 23379991, 2013). "Immunostaining showed that the tumor was strongly positive for Vimentin, Desmin and MyoD1, and was negative for CK, P63, NSE, CD45, CD30, S-100, CD99, Myoglobin, CD68, CD34, CD31, α–SMA." (PMID 23379991, 2013). "In the immunochemistry, Inhibine, CD99, EMA, chromogranin, synaptophysin were negative; the tumour cells strongly expressed PS100 and Melan A HMB45 was observed in some cells suggesting the diagnosis of metastatic ovarian amelanic melanoma." (PMID 21682901, 2011). "Immunohistochemically, the tumor cells were strongly positive for CD34, CD99, Bcl-2, and vimentin and negative for smooth muscle actin (SMA), CD31, cytokeratin, S-100, CD117, and epithelial membrane antigen (EMA)." (PMID 21443810, 2011). "In our case, the tumor cells were strongly positive for CD34, CD99, Bcl-2, and vimentin and negative for smooth muscle actin (SMA), CD31, cytokeratin, S-100, CD117, and epithelial membrane antigen (EMA)." (PMID 21443810, 2011). "APOE− tumor cells may promote tumor growth by interacting with dendritic cells and CD4+ T cells via CD99‐ rather than CD6‐regulated signaling." (PMID 39810624, 2025). "At the same time, tumor cells were negative for MPO, CD99, NKX2.2 and CD61." (PMID 40565358, 2025). "However, CD34 is not a specific immunomarker of SFT and it can be negative in about 10% of SFTs, furthermore, CD99 and BCL2 are usually expressed in many other neoplasms." (PMID 40027129, 2025). "Desmin, CD99, and CD31 were negative, while ERG expression was noted in scattered tumour cells." (PMID 39001214, 2024). "The tumor cells were negative expression of epithelial markers, including PCK, EMA, CK8/18, CK20 and low molecular weight keratin (CAM5.2), as well as CgA, CD56, S100, HMB45, CD117, DOG1, CD99, WTI, Desmin and SMA." (PMID 38877473, 2024). "Tumor cells express desmin and CD34 but are negative for CD99, Bcl-2, and STAT6." (PMID 39206171, 2024). "The tumor immunohistochemistry results were B‐cell lymphoma 2 (BCL‐2) positive, focal CD34 +, focal cytoplasmic CD99+, epithelial membrane antigen (EMA) and Panker negative, actin negative, S100 protein‐negative, Papanicolaou and Block cell with a positive result for malignant tumor cells." (PMID 35414906, 2022). "On immunohistochemistry, the tumor cells were immunoreactive for neuron-specific enolase (NSE), synaptophysin, chromogranin, CD56, Bcl-6, CD99, and peripherally for S100, but nonreactive for cytokeratin (CK), smooth muscle actin (SMA), and epithelial membrane antigen (EMA)." (PMID 36452830, 2022).
tumor (continued). "However, the tumor cells were negative for S-100 protein, SMA, desmin, myogenin, CD99, Fli-1, CD56, STAT6, CK and EMA." (PMID 32957984, 2020). "Immunohistochemically, the tumor cells were positive for epithelial markers (AE1/AE3, EMA), a smooth muscle marker (desmin), and less specific sex-cord markers (CD56, WT-1, CD99), but negative for relatively specific sex-cord markers (α-inhibin, calretinin, FOXL2, and SF1)." (PMID 32921307, 2020). "The tumor cells are immunostain positive for INSM1, SOX9, CD99 and S100, but negative for MUC4." (PMID 32164724, 2020). "Immunohistochemical profile of tumor was similar to the first case including strong and diffuse MUC4, vimentin and bcl-2, weak EMA expression except negative immunoreactivity for CD99." (PMID 26449317, 2015). "In Prostatic stromal sarcoma (PSS) unlike the PES, immunohistochemically, the tumour cells are widely positive for vimentin, CD56, CD99 and focally positive for synaptophysin, CD10, progesterone receptor, desmin and CD34, but negative for EMA, cytokeratin, estrogen receptor, S-100 and myoglobin." (PMID 23886403, 2013). "By immunohistochemistry, the tumor cells expressed synaptophysin, chromogranin, NKX2.2 (diffuse, nuclear), GFAP (patchy), SMI31 (neurofilament) (focal, cytoplasmic), and TdT (diffuse, nuclear), while lacking expression of CD99, TTF-1, CK 20, MCPyV, PHOX2B, Olig2, OCT3/4, CD45, CD3 and PAX5." (PMID 38031161, 2023). "Immunostaining with CD99 and NKX2.2 could not identify viable tumor cells." (PMID 36451511, 2022). "Immunohistochemical analysis of CD99, HRNR, and CANX confirmed the expression of these markers in the prostate but, due to high heterogeneity, with high- and low-expression areas in both healthy and tumor tissues, it was not possible to compare the two conditions." (PMID 35267445, 2022). "Tumor cells were enlarged with large edematous nuclei and significant infiltration of lymphocytes, and immunostaining showed that the tumor cells were bcl-, CD5-, and p40-positive, and the lymphocytes were CD3-positive and CD99-negative, leading to the diagnosis of TLEC." (PMID 34638279, 2021). "Additionally, the tumor was negative for most immunohistochemical markers (CKAE1/AE3, p63, CD23, CD21, MUC4, NUT, CDK4, Pan-TRK, STAT6, SS18, MDM2, Desmin, S100, ERG, TLE1, Fli) and showed only weak and most probably unspecific expression of CD99, CD56, and CD34." (PMID 39519042, 2024).
cancer (65 papers, 2007 to 2026). A tumor composed of atypical neoplastic, often pleomorphic cells that invade other tissues. "Research indicates that the expression levels of general stem cell markers (such as CD34 and CD73), genes linked to cancer stem cells (CD99 and ITGB3), and an embryonic stem cell marker (GGT1) are elevated within this subset." (PMID 41204265, 2025). "An opposite association for CD99 was observed with sporadic basal cancers showing increased expression compared to BRCA1 cancers (p = 0.024)." (PMID 26152113, 2015). "Identification of CD99/MIC2 as an EFT-associated marker has greatly facilitated the differential diagnosis of these cancers, besides specific chromosomal translocations coding for Ewing sarcoma gene (EWS) fusion proteins." (PMID 29147265, 2011). "Importantly, we found significantly increased cell migration when expressing the cancer-associated CD99 variant D92H compared to the wild-type protein." (PMID 28903388, 2017). "Literature evidences have also demonstrated that the supernatants from several carcinoma cell lines associated with osteolytic metastases (breast, colon, pancreatic, renal, and hepatoma cell lines) specifically downregulate CD99 on AHTO-7 cells (large T antigen transfected human trabecular OBs)." (PMID 26000312, 2015). "This review explores CD99’s role in normal physiology and cancer biology, focusing on how monoclonal antibodies affect CD99 expression and activity, thereby influencing cancer cells’ interactions with their microenvironment." (PMID 40427525, 2025). "CD99 is a marker for cancer stem cells and stands out as a promising therapeutic target within these malignancies." (PMID 40427525, 2025). "CD99 is crucial at the intersection of normal biological processes and pathological conditions like cancer." (PMID 40427525, 2025). "This study emphasizes the regulatory roles of CD99 and PILRa in the communication between luminal cancer cells and macrophages in breast cancer." (PMID 40427525, 2025). "This review examines the role of CD99 in various aspects of normal physiology and cancer biology, focusing on its functions in immune cells." (PMID 40427525, 2025). "It discusses how monoclonal antibodies can affect CD99 expression and activity, influencing homotypic and heterotypic interactions between cancer cells and their microenvironment." (PMID 40427525, 2025). "For cancer, the alteration of CD99 expression levels has been demonstrated in a broad range of cancers." (PMID 38468825, 2024). "Nevertheless, some preclinical studies show selectivity for cancer cells compared with normal CD99-expressing cells, and the use of low affinity antibodies has been shown to be effective in leukemic models while sparing normal bone marrow cells." (PMID 38607036, 2024). "The mAbs targeting CD99 expressed on these cancers were found to be directly cytotoxic in inducing cancer apoptosis." (PMID 38468825, 2024). "These preclinical studies collectively highlight the diverse and promising ways in which CD99 can be targeted for cancer treatment." (PMID 38607036, 2024). "Their findings suggest that CD99-directed therapies hold significant potential for effectively combating various types of cancers, and further exploration of these strategies in clinical studies is warranted." (PMID 38607036, 2024). "In preclinical studies, monoclonal antibodies targeting CD99 have shown promise in various cancer types." (PMID 38607036, 2024). "CD99 marks malignant myeloid stem cells, and recently, it was reported as a potent indicator of cancer stem cells, presenting a potentially effective therapeutic target in these malignancies." (PMID 38239853, 2023). "Although well established in leucocyte TEM, the involvement of CD99 in cancer progression remains enigmatic." (PMID 34374417, 2021). "The adhesion molecule CD99 is overexpressed in many types of cancer, particularly in Ewing sarcoma and specific subtypes of leukemia." (PMID 34692768, 2021).
cancer (continued). "Then we chose CD99 as a reference for anti-cancer mechanism studies of EPS11 based on proteomic analysis." (PMID 30641946, 2019). "CD99 appears to be a robust marker of cancer stem cells and a promising therapeutic target in these malignancies." (PMID 29305692, 2018). "This review discusses recent mechanistic studies that have had a major influence in the understanding of the role of CD99 in various aspects of physiology, cancer biology and therapeutics." (PMID 29305692, 2018). "Forced expression of CD99 inhibits cancer metastasis through the suppression of C-SRC and ROCK2 activities, while increasing osteoblast differentiation through ERK/RUNX2-mediated reactivation of osteoblastogenesis." (PMID 29305692, 2018). "The adhesion molecule CD99 was shown to be important for correct immune cell extravasation and is highly expressed on certain cancer cells." (PMID 28903388, 2017). "CD99 promotes cancer cell death when triggered by specific antibodies, such as 0662, O13 murine mAbs or the human single chain fragment variable diabody (dAbd C7)." (PMID 27835596, 2016). "High or low CD99 levels have been detected in various pathological conditions, and the supernatant of some carcinoma cell lines can modulate CD99 expression in OB-like cells." (PMID 26000312, 2015). "CD99 antigen, encoded by the MIC2 gene, is a 32 kDa transmembrane protein widely expressed in nearly all human cell types, particularly in hematopoietic cells, the thymus, endothelial cells, Sertoli cells, and cancer cells." (PMID 40427525, 2025). "While alterations in CD99 expression have been observed across a wide range of neoplastic human tissues, the precise relationship between CD99 expression and the development of human cancers remains somewhat contentious, often exhibiting opposing functions based on the cellular context." (PMID 40427525, 2025). "CD99 regulates various biological processes such as adhesion, transendothelial migration, differentiation, and cell death, thereby affecting immune function, inflammation, and cancer metastasis." (PMID 40427525, 2025). "The targeting of CD99 epitopes by several antibody clones could induce cancer cell death and showed anti-cancer effects on ES, AML, and MDS in mouse xenograft models." (PMID 39595598, 2024). "Therefore, CD99 has been proposed to be a potential therapeutic target for an antibody drug in CD99 overexpressed cancers." (PMID 38468825, 2024). "Thus, CD99 has been suggested to be a promising therapeutic target molecule for an antibody drug in these CD99-overexpressing cancers." (PMID 39595598, 2024). "The meprin β substrate CD99 was observed to promote cancer cell extravasation." (PMID 34692768, 2021). "CD99-silenced EwS cells exhibited reduced migratory ability, and their CD99-negative exosomes contained miR-199a-3p, thereby inhibiting growth and migration of recipient cells as seen in other cancers." (PMID 34604225, 2021). "In addition, CD99 is highly expressed in several other cancer types, and its specificity for EwS among differential diagnoses was found to be remarkably low in our previous study (17% at a cut-off of 2)." (PMID 32164354, 2020). "Considering the importance of CD99 in regards to cell adhesion, migration and cancer metastasis and its significant down-regulation by EPS11 based on the proteomic result, we explored the expression of CD99 in both mRNA and protein levels after treatment with EPS11." (PMID 30641946, 2019). "Thus, CD99 can be used as a robust marker for several tumors and a promising therapeutic target in cancer, particularly in tumors arising from the transformation of stem/precursors cells." (PMID 29305692, 2018). "The discrepant roles of CD99 in different tumors may be due not only to the difference in cancer types but also to the difference in the relative expression levels between the two CD99 isoforms." (PMID 29534016, 2018).
cancer (continued). "Although alterations in CD99 expression have been demonstrated in a broad range of neoplastic human tissues, the actual relationship of CD99 expression with the development of human cancers has been somewhat controversial, often with opposing functions, depending on the cellular context." (PMID 29305692, 2018). "We hypothesized that loss of the negatively charged and preferred Asp92 would alter meprin β-mediated cleavage of CD99 and subsequent γ-secretase processing with possible impact on cancer cell biology." (PMID 28903388, 2017). "In addition, 3 samples presented CD99 expression in carcinoma cells and 9 cases presented CD99 expression in sarcomatoid cells (P = 0.116)." (PMID 28449664, 2017). "Of the six proteins that were investigated via immunohistochemistry, four (cyclin D1, FOXP1, NRP1 and CD99) showed reduced expression in BRCA1 cancers in the initial cohort with reduced expression for FOXP1, cyclin D1 and NRP1 subsequently confirmed in the validation cohort." (PMID 26152113, 2015). "It was shown that some carcinoma cell line-conditioned media downregulate CD99 on human AHTO-7 OBs." (PMID 26000312, 2015). "It was found that CD99, a surface marker of EwS cancer cells, could be released through exosomes." (PMID 34604225, 2021). "Furthermore, CD99 is positively stained in immunohistochemical preparations of HCC tissue material and negatively stained in non-HCC tissues outside the liver or metastatic within the liver, which strongly suggests that CD99 is essential in the course of cancer development and metastasis of HCC." (PMID 30641946, 2019). "After showing that both CD99 variants can be shed by meprin β and that they have no influence on Src activation, we investigated their effect on cell proliferation and migration where changes are typically associated with cancer and metastasis." (PMID 28903388, 2017). "For incoming signalling of CAFs, CD99, PDGF, MK and FGF have been identified as functional members in most cancers." (PMID 36772945, 2023). "For cell–cell contacts, CD99, MPZ and THY1 were the common cellular interaction media in most cancers." (PMID 36772945, 2023). "CD99 antigen and CD99 antigen-like protein 2 (CD99L2) are related transmembrane proteins that form heterodimers and play important roles in leukocyte extravasation and cancer." (PMID 39684750, 2024). "Although the combination of several antibodies, including CD99, EMA, and S100, has been proposed for diagnosing SS using immunohistochemistry (IHC), it is difficult to obtain the correct diagnosis due to overlap with other benign and malignant tumors." (PMID 38786310, 2024). "The CD99 molecule is broadly expressed on human hematopoietic cells and non-hematopoietic cells, as well as several types of cancer cells." (PMID 38468825, 2024). "For cancer biology, our functional annotation analyses demonstrate that CD99-negative cells and related EVs are characterized by a migration-suppressive, pro-immunostimulatory proteomic profile compared to their CD99-positive counterparts." (PMID 38338867, 2024). "Outgoing signaling patterns upregulated in LE-LE signaling, relative to TC-TC signaling, included Collagen, Laminin, Tenascin, FN1, MIF, APP, CD99, Notch, and CSPG4 pathways, reinforcing the role of these pathways in facilitating cancer invasion and metastasis." (PMID 37596273, 2023). "Moreover, lymph cells highly express other signaling pathways that can be ultimately connected to interactions between cancer cells and T cells, such as APP, CD99, MHC-I, and CD46." (PMID 34830900, 2021). "Thus, we propose that CD99 is a potential action target of EPS11, inhibiting cancer cell proliferation, adhesion and migration." (PMID 30641946, 2019). "The expression of Cyclin D1, FOXP1, FIH-1, pan-ERβ, NRP1 and CD99, predicted to be regulated by BRCA1 specific miRNAs by computer prediction algorithms, was assessed via immunohistochemistry in a cohort of 35 BRCA1 and 52 sporadic basal-like cancers." (PMID 26152113, 2015).
cancer (continued). "Increased expression for CD99 in BRCA1 cancers was not reproduced in the validation cohort, where reduced expression was observed." (PMID 26152113, 2015). "The varying roles of CD99 across different tumors could stem not just from the cancer types but also from the differing expression levels of its two splicing isoforms (type I and type II)." (PMID 40427525, 2025). "Furthermore, CD99 expression is observed in early stages or benign tumours, but absent or reduced in advanced stages or malignant tumours." (PMID 40933515, 2025). "These variants can act extracellularly on CD99 to induce cell death in EWS cells without affecting DNA synthesis, exhibiting greater specificity for targeting CD99 expressed in cancer cells while demonstrating much lower toxicity towards normal proliferating cells." (PMID 40427525, 2025). "BRCA1 basal cancers, when compared to sporadic basal cancers showed reduced positivity for FOXP1 (6/20 [30 %] vs. 37/49 [76 %], p < 0.001), cyclin D1 (8/22 [36 %] vs. 30/46 [65 %], p = 0.025), NRP1 (2/20 [10 %] vs. 23/46 [50 %], p = 0.002) and CD99 (17/20 [85 %] vs. 7/19 [37 %], p = 0.002)." (PMID 26152113, 2015). "Stimulated MMP-2 production in co-culture of cancer cells and fibroblasts was completely suppressed by siRNA knockdown of CD73, but not by CD99 knockdown." (PMID 31510956, 2019). "While the small number of cancer samples did not allow assessment of statistical significance, several of the new markers identified through mRNA analysis also showed trends of increased protein expression in SQCCs relative to ADCs (CD71/TFRC, CD9, PDPN, CD138/SDC1, CD99)." (PMID 25551685, 2014).